GNAZ (G protein subunit alpha z)
Description:
Guanine nucleotide-binding proteins (G proteins) are involved as modulators or transducers in various transmembrane signaling systems.
Synonyms: HG1H; gz-alpha
Tractability: Small molecule: a structure with a bound ligand is known. Antibody: its Gene Ontology location is reachable by antibodies, with high confidence. PROTAC: ubiquitination databases record sites on it; its protein half-life has been measured.
Gene: Protein-coding gene on chromosome 22 (23,070,325 to 23,125,036, forward strand). Ensembl gene ENSG00000128266.
Subcellular location: Membrane
Subcellular location (Human Protein Atlas): Vesicles
Pathways (Reactome):
Signal Transduction: G alpha (i) signalling events; G alpha (s) signalling events; G alpha (z) signalling events; GPER1 signaling
Disease: ADORA2B mediated anti-inflammatory cytokines production
Gene Ontology:
Molecular function: protein binding; G protein-coupled receptor binding; G-protein beta/gamma-subunit complex binding; GTPase activity; adenylate cyclase inhibitor activity; GTP binding; guanyl nucleotide binding
Biological process: adenylate cyclase-modulating G protein-coupled receptor signaling pathway; G protein-coupled receptor signaling pathway; negative regulation of insulin secretion; signal transduction
Cellular component: endoplasmic reticulum; nuclear envelope; plasma membrane; cell body; dendrite; membrane; synapse
Genetic constraint (gnomAD): Loss-of-function variants: 3 observed, 25.68 expected, observed/expected ratio (o/e) 0.12, 90% interval 0.052 to 0.3. The upper end of that interval is the gene's LOEUF score, 0.3, which puts it in group 1 of 6, group 1 being the genes least tolerant of losing a copy. Missense variants: 241 observed, 517.61 expected, observed/expected ratio (o/e) 0.47, 90% interval 0.42 to 0.52. Synonymous variants: 211 observed, 214.21 expected, observed/expected ratio (o/e) 0.99, 90% interval 0.88 to 1.1.
Homologues: Orthologues: chimpanzee GNAZ (100% identical), macaque GNAZ (100% identical), dog GNAZ (99% identical), rabbit GNAZ (99% identical), guinea pig GNAZ (99% identical), mouse Gnaz (98% identical), rat Gnaz (98% identical), pig GNAZ (97% identical), tropical clawed frog gnaz (96% identical), zebrafish GNAZ (94% identical), Caenorhabditis elegans gpa-3 (45% identical), Drosophila melanogaster CG30054 (43% identical), and 11 more. Paralogues in human: GNAI1 (67% identical), GNAI3 (67% identical), GNAI2 (66% identical), GNAO1 (59% identical), GNAT3 (57% identical), GNAT2 (57% identical), GNAT1 (54% identical), GNA14 (48% identical), GNAQ (48% identical), GNA11 (46% identical), GNA15 (43% identical), GNAL (43% identical), and 3 more.
Diseases named in the same sentence as GNAZ in open-access papers:
GNAZ is named in the same sentence as 10 diseases in open-access papers, as found by Europe PMC text mining. Sharing a sentence is not in itself a finding about the gene and the disease. The quoted sentences say what the papers report.
cervical cancer (1 paper, 2025). A primary or metastatic malignant neoplasm involving the cervix. "Studies have found that the molecular typing of pyroptostic‐related genes (PRGs) in cervical cancer can predict prognosis, and the GNAZ/LAG3/IL1B/CA2/SPRR3 risk scoring model has been constructed." (PMID 41025546, 2025). "However, the expression of CA2, GNAZ, and SPRR3 did not appear to affect cervical cancer prognosis." (PMID 41025546, 2025).
diabetic retinopathy (1 paper, 2023). "Previously, the rhythmic regulation of GNAZ was shown to be disturbed by hyperglycemia, suggesting a putative role of GNAZ in the pathogenesis of diabetic retinopathy." (PMID 37095509, 2023).
hepatocellular carcinoma (1 paper, 2022). A malignant tumor that arises from hepatocytes. "G protein subunit alpha Z (GNAZ) is a potential oncogene in hepatocellular carcinoma, promoting tumor proliferation through cell cycle arrest, apoptosis, migration and invasion." (PMID 36110946, 2022).
tumor (4 papers, 2019 to 2025). "In the mRNA group, ZIC5, C12orf75, C1QL1, TMEM74, and GNAZ were significantly upregulated in tumor tissues compared to the adjacent control; PZP and FAM65C were significantly downregulated compared to the adjacent control." (PMID 31156698, 2019). "Moreover, HCC patients with higher GNAZ expression had a significantly worse prognosis than those with lower levels, which suggest that GNAZ acts as a tumor-promoting gene in HCC." (PMID 41306771, 2025). "Moreover, the mice injected with the GNAZ-overexpressed HepG2 cells showed increasing tumor weight and VM density than the controls." (PMID 41306771, 2025). "In this study, we found that markedly increased IF1 expression patterns in HCC contribute to tumor growth and VM formation via the ESR1 and miR-20a-3p/GNAZ/ERK pathway." (PMID 41306771, 2025). "TCGA data showed that GNAZ expression clearly increased in tumor relative to surrounding non-carcinoma sample." (PMID 41306771, 2025).
retinopathy (1 paper, 2023). "However, the spatial co-distribution patterns of GNAZ, ADAM17, and CLDN5 in endothelial cells partially confirmed the susceptibility of retinal endothelial cells to blue light as well as the role of retinal endothelial cells in blue-light-mediated retinopathy." (PMID 37095509, 2023).
GNAZ also shares sentences with these, for which no sentence is quoted: cancer (3 papers); Hyperglycemia (1); night blindness (1); psychiatric disorder (1); Rod-cone dystrophy (1).